BRCA2 (BRCA2 DNA repair associated)
Diseases named in the same sentence as BRCA2 in open-access papers (continued):
Sharing a sentence is not in itself a finding about the gene and the disease.
prostate carcinoma (continued). "Prostate cancer cells with BRCA2 deficiency may tolerate the genomic and chromosomal instability caused by BRCA2 deficiency by silencing SAC activation in the process of cancer occurrence and progression." (PMID 37934606, 2024). "We further substantiated in LNCaP cells that the microtubule instability resulting from BRCA2 deficiency could be effectively reversed in prostate cancer cells by use of a specific chemical inhibitor of AURKB." (PMID 37934606, 2024). "However, the presence of BRCA2 mutations has been associated with an increased risk of prostate cancer." (PMID 39364320, 2024). "However, concerns were raised about the feasibility of initiating proactive conversations in men with a family history of prostate cancer or BRCA2 gene mutation, given the poor recording of both in primary care." (PMID 39038964, 2024). "Moreover, SAC inactivation is common in BRCA2-deficient prostate cancer patients and many BRCA2-deficient cell lines, and PP2A inhibitors (PP2Ais) that can restore SAC activity are potential drugs for the synthetic lethality of BRCA2-mutated cancer cells." (PMID 37934606, 2024). "Moreover, BRCA2 PVs were associated with three- to fourfold increased risks of pancreatic and stomach cancers in both sexes, as well as with a twofold increased risk of prostate cancer, with a cumulative risk to age 80 years of 27% for male BRCA2 PV carriers." (PMID 38339330, 2024). "Interestingly, male carriers of pathogenic BRCA2 mutation variants have a lower risk of developing prostate cancer (PCa) when the variant is located within BRCA2 OCCR1." (PMID 38203374, 2023). "Furthermore, the prevalence of prostate cancer is much higher in patients with a family history of a BRCA2 pathogenic variant." (PMID 37174127, 2023). "In the BRCA1- and BRCA2-associated hereditary cancer syndromes, there is a higher risk of prostate cancer and gastrointestinal cancers (pancreatic, gastric, biliary tract, esophageal), while the risk of melanoma, colorectal, and lung cancer is still a matter for debate." (PMID 37239385, 2023). "Notably, reversion mutations in BRCA2 mediating PARPi resistance have been reported in ovarian, breast, pancreatic and prostate cancer, highlighting the benefit of implementing molecular profiling to pre‐emptively detect them in clinical settings." (PMID 36779660, 2023). "Furthermore, mutations in BRCA2 are more often associated with other types of epithelial cancer, including male BC, pancreatic cancer, and prostate cancer, than BRCA1 mutations." (PMID 36902416, 2023). "A prospective observational research report on the incidence of prostate cancer in western populations focused on a group of BRCA1/BRCA2 pathogenic variant carriers and a control group that underwent predictive testing and finally tested negative for a pathogenic germline BRCA1/BRCA2 variant." (PMID 37174127, 2023). "Additionally, the possibly heightened rate of BRCA2 mutations in IDC-P patients further adds complexity to the genetic profile of this subtype of prostate cancer." (PMID 38067216, 2023). "Loss of heterozygosity or deletion also occurs within the 13q21 region in PCa, may include BRCA2, and is associated with high-grade prostate cancer." (PMID 37095257, 2023). "Germline BRCA2 pathogenic variant carriers are associated with prostate cancer risk." (PMID 36612302, 2023). "In addition to elevated cancer risk, germline BRCA1 or BRCA2 mutations in breast, ovarian and prostate cancer, predict both a better prognosis and superior response to cisplatin-based chemotherapy." (PMID 37020472, 2023). "Mutations in the BRCA1 and BRCA2 genes increase the risk of developing prostate cancer." (PMID 36902416, 2023). "Studies have shown that BRCA2-associated prostate tumors exhibit an aggressive phenotype and are often associated with the presence of the intraductal carcinoma of the prostate pathology, a poor prognostic feature for prostate cancer." (PMID 37511593, 2023).
prostate carcinoma (continued). "Both somatic and germline BRCA2 mutations can be detected in up to 10% of all prostate cancers." (PMID 38067216, 2023). "BRCA2 is well known to be associated with aggressive prostate cancer." (PMID 35079693, 2022). "As a result, six BRCA2 variants, which VAFs ranged from 43.7 to 60.0% in ctDNA testing, were confirmed to be germline in patients with pancreatic (n = 2), breast (n = 2), ovarian (n = 1), and prostate cancers (n = 1)." (PMID 35870019, 2022). "The interim analysis of the study has reported that after 3 years of PSA screening in men with germline BRCA1/2 mutations, those with a BRCA2 mutation had increased incidence of prostate cancer, younger age at diagnosis, and higher risk of developing clinically significant tumours." (PMID 36010882, 2022). "BRCA2 is the best-established prostate cancer susceptibility gene." (PMID 35732815, 2022). "In patients with intraductal carcinoma, the incidence of BRCA2 germline mutations reported in the literature is higher than for adenocarcinoma, while the data for somatic mutations are similar to the rest of patients with prostatic carcinoma." (PMID 35326693, 2022). "However, currently, the National Comprehensive Cancer Network (NCCN) recommends the recruitment of all males carrying BRCA1 or BRCA2 pathogenetic variants within the same screening programs, especially for breast and prostate cancer." (PMID 35454911, 2022). "Parallel cell line generation of isogenic gene knockouts in ovarian and prostate cancer cell lines identified that inactivation of core HRR factors is required for driving in vitro PARPi responses comparable with the ones observed for BRCA1 or BRCA2 mutations." (PMID 36969741, 2022). "However, a mutation in BRCA2 has also been found in other tumors, such as ovarian, pancreatic, thyroid, gastric, laryngeal, and prostate cancers." (PMID 36397405, 2022). "Our previous findings suggested the joint effects of PRS and BRCA1 and BRCA2 pathogenic variants may identify men at clinically meaningful breast and prostate cancer risk levels." (PMID 34320204, 2022). "Early studies showed that BRCA1 and BRCA2 mutations have an increased risk of prostate cancer." (PMID 36294924, 2022). "Recent studies have indicated that prostate cancer (PCa) with BRCA2 mutations is more aggressive." (PMID 35251954, 2022). "Similarly, mutations in the BRCA2 gene are also associated with increased chances of developing male breast cancer and cancers of the prostate and pancreas." (PMID 36010323, 2022). "Our data with RAD51B are consistent with published literature and our results with ATM are in agreement with the differential responses observed in patients with prostate cancer harboring tumors with mutations in ATM treated with olaparib when compared with those carrying BRCA2 mutations." (PMID 36969741, 2022). "Consequently, BRCA2 germline mutations increase the risk of prostate cancer 8.6-fold by the age of 65 years." (PMID 36010882, 2022). "In the case of BRCA2 mutations, the risk of developing prostate cancer by 65 is 15%." (PMID 35303741, 2022). "Moreover, prostate cancer with BRCA2 had better outcome as compared to those with BRCA1 mutations, after treatment with PARP inhibitors." (PMID 36010882, 2022). "However, multiple studies have noted that patients with prostate cancer harboring BRCA2 mutations are more responsive to PARP inhibitors compared to BRCA1 mutation-positive patients." (PMID 36185208, 2022). "PARP inhibitors (PARPi) are current treatment options for patients with ovarian, breast, pancreatic, and prostate cancer harboring mutations in BRCA1 or BRCA2 (BRCAm) but they have also been approved in broader patient populations in ovarian and prostate cancer." (PMID 36969741, 2022).
prostate carcinoma (continued). "Apparently, those with BRCA2 mutations respond better to PARP inhibitors as compared to the prostate cancer patients with ATM and CHEK2 alterations; nevertheless, the same correlation with higher genomic scarring composite scores has been revealed in the respective DDR gene mutations." (PMID 36010882, 2022). "The higher number of significant concurrently mutated genes in other molecular pathways may explain the decreased efficacy of PARP inhibitors in prostate cancer harboring BRCA1 mutations compared to those with BRCA2 mutation." (PMID 36185208, 2022). "Studies have demonstrated that BRCA2 mutations increase the risk of prostate cancer by 8.3-fold." (PMID 36397405, 2022). "In a pooled analysis of 5 studies, men with BRCA1 mutated prostate cancer compared to BRCA2 mutated had a lower PSA50 response rate (23.8% vs. 65.2%), lower overall response rate (26.3% vs. 50%) and a lower median radiographic progression-free survival (4.1 months vs. 10.1 months)." (PMID 36185208, 2022). "We hypothesized this differential efficacy may be explained by distinct genomic landscapes of prostate cancer harboring BRCA1 versus BRCA2 mutation." (PMID 36185208, 2022). "Our observation that KMT2D is more commonly mutated in BRCA2d suggests that it plays a role in BRCA2-associated prostate carcinogenesis and may identify therapeutic targets for BRCA2d prostate cancer." (PMID 35715489, 2022). "It has been shown that the BRCA2-mutant in prostate cancer might be associated with the histological characteristics of intraductal carcinoma of the prostate (IDC-P), and a tendency for higher incidence of biochemical relapse after surgery." (PMID 35008774, 2021). "BRCA2 mutations may also lead to more rapid taxane resistance in metastasized castration-resistant prostate cancer patients." (PMID 34439347, 2021). "Furthermore, we separated BRCA1 and BRCA2 in the subgroup analysis, and found that BRCA2 is likely the most important mutation in prostate cancer, and the impact of BRCA1 needs to be clarified in future studies." (PMID 34975480, 2021). "Relatives with germline BRCA1 and BRCA2 mutations could be at increased risk of male breast, colon, pancreatic and prostate cancer." (PMID 34884434, 2021). "However, they later performed another meta-analysis and showed that prostate cancer incidence is increased by BRCA1 or BRCA2 mutation." (PMID 34577828, 2021). "It is not yet known whether PSA screening will reduce mortality from prostate cancer in men with cancer-predisposing BRCA2 variants." (PMID 34649841, 2021). "To date, few studies have explored this possibility, although differences in response to PARPis in prostate cancer have been reported based on whether the tumour was BRCA1 or BRCA2 mutated." (PMID 34445211, 2021). "The patient harbored a deleterious BRCA2 germline variant was also concurrent with prostate cancer." (PMID 33588785, 2021). "Moreover, in the ATM, BRCA1 and BRCA2 genes from prostate cancer patients, the distributions of germline benign, pathogenic, VUS, and recurrent somatic variants differ across Pfam domains." (PMID 34253785, 2021). "Our study applied a new recommended definition of aggressive prostate cancer and provides further evidence that rare germline pathogenic variants in ATM, BRCA1, and BRCA2 are associated with increased risk of this aggressive, clinically relevant subset of prostate cancer." (PMID 33804961, 2021). "Recently, an increasing number of studies have been performed to prove that the BRCA2-N372H variant is related to susceptibility to many other cancers, including multiple lymphoma, prostate cancer, advanced esophageal squamous cell carcinoma, familial colorectal tumors, and so on." (PMID 34367235, 2021). "Furthermore, in prostate cancers, simultaneous loss of BRCA2 and RB1 sensitizes tumor cells to PARP inhibitor." (PMID 34359636, 2021). "BRCA2 mutations also predispose to prostate cancer which was also associated with ALL22." (PMID 34117277, 2021).
prostate carcinoma (continued). "One patient with gynecomastia and prostate carcinoma harbored a germline BRCA2 mutation." (PMID 32295201, 2020). "In addition, BRCA2 PV/LPVs have been associated with an increased risk of prostate cancer, pancreatic cancer, and uveal melanoma." (PMID 32046255, 2020). "In addition, BRCA2 alterations have been associated with an increased risk of prostate cancer, pancreatic cancer, and uveal melanoma." (PMID 32365798, 2020). "In this report, we investigated whether the risk of prostate cancer for men with a harmful mutation in the BRCA2 gene differs based on where in the gene the mutation is located." (PMID 32532514, 2020). "However, clinical implications of germline and somatic HRR gene alterations, besides germline BRCA2 mutations, in prostate cancer remain uncertain due to limited studies, number of patients enrolled, and available approved treatments." (PMID 33233320, 2020). "In this study we followed unaffected men known to carry mutations in the BRCA1 and BRCA2 genes to investigate whether they are at higher risk of developing prostate cancer compared to the general population." (PMID 31495749, 2020). "Individuals who may have family history of prostate cancer and positive for BRCA2 mutation have higher rates of progression/grade reclassification while on active surveillance (AS), and lower metastasis free and overall survival after primary treatment." (PMID 32957584, 2020). "The ESMO clinical practice guidelines state that annual screening for prostate cancer may be considered from age 40 onwards, particularly for BRCA2 mutation carriers." (PMID 32655641, 2020). "We found that carriers of BRCA2 mutations have a high risk of developing prostate cancer, particularly more aggressive prostate cancer, and that this risk varies by family history of prostate cancer and the location of the mutation within the gene." (PMID 31495749, 2020). "Germline BRCA2 mutations in prostate cancer patients are associated with worse clinical outcomes." (PMID 32029455, 2020). "Also, it has been showed that the men who are in families facing with a hereditary form of the prostate cancer caused by BRCA2 mutation increase risk of affliction with prostate cancer." (PMID 32592348, 2020). "A larger cross-sectional analysis of 1328 men with prostate cancer by Giri and colleagues found 15.6% carriers of germline mutations; 10.9% patients carried a mutation in DNA repair genes (BRCA2 > CHEK2 > ATM > BRCA1), increasing the risk of more advanced tumors (Gleason score ≥ 8)." (PMID 33322746, 2020). "Also other studies have showed similar results finding approximately 12% and 8% of prostate cancer patients carrying a BRCA2 or ATM mutation, respectively." (PMID 31357527, 2019). "In addition, we analyzed seven prostate cancer biopsies that were either BRCA2 or ATM-mutated in comparison with wild-type tumors." (PMID 31549213, 2019). "Prostate cancer associated with BRCA2 mutation may be particularly responsive to platinum‐based chemotherapy." (PMID 31631483, 2019). "BRCA2 reversion conferred resistance of castration-resistant prostate cancer cells to olaparib, consistently with previous studies in breast and prostate cancer patients showing acquired resistance to olaparib in BRCA2-associated cancers due to BRCA2 reversion mutations." (PMID 31284411, 2019). "Collectively, our results underscore that the BRCA2 mutation status shapes the immune phenotype of prostate cancer with an increase of intratumoral immune cells that may in part be immunosuppressive." (PMID 31549213, 2019). "Men harboring an inherited BRCA2 mutation have a 30% lifetime-risk of developing prostate cancer, although it may vary from 19% to 61% depending on the presence/absence of genetic variants acting as risk-modifiers." (PMID 30871108, 2019). "Taken together, our findings show that the FDA-approved 6-TG may represent a promising therapeutic drug for treatment of BRCA2-deficient castration-resistant prostate cancers." (PMID 31284411, 2019).
prostate carcinoma (continued). "This could reflect the absence of CDK12 mutations and the presence of only three sporadic BRCA2-mutated samples (1%) in the primary prostate cancer cohort." (PMID 31748536, 2019). "Hence, the presence of intratumoral T lymphocytes is necessary but clearly not sufficient for a response to immune checkpoint inhibitors, which makes treatment responses in BRCA2-mutated prostate cancer difficult to predict." (PMID 31549213, 2019). "Our findings provide a rationale for the future use of immune oncological agents in BRCA2-mutated prostate cancer patients and may encourage efforts to target immunosuppressive T-cell populations." (PMID 31549213, 2019). "In prostate cancer patients, BRCA2 reversion mutations have been associated with PARPi resistance." (PMID 31357527, 2019). "Our findings provide a rationale for the future use of immune oncological approaches in BRCA2-mutated prostate cancer and may encourage efforts to target immunosuppressive T-cell populations to prime tumors for immunotherapy." (PMID 31549213, 2019). "The elevated risk for prostate cancer in BRCA2 carriers is well known." (PMID 30136106, 2019). "BRCA2 carriers are associated with poor prognosis and more aggressive form in prostate cancer." (PMID 31477094, 2019). "BRCA2-mutated prostate cancers are sensitive to PARP inhibitors." (PMID 31366128, 2019). "In addition, we characterized the immune infiltrate in seven prostate cancer biopsies that were either BRCA2 or ATM mutated or wild type." (PMID 31549213, 2019). "The risk of prostate cancer is up to fivefold higher in BRCA2 mutation carriers." (PMID 29433453, 2018). "Deleterious BRCA1 or BRCA2 mutations may also moderately increase the risk of breast and prostate cancer in men, and pancreatic cancer or colorectal cancer in both sexes." (PMID 30518089, 2018). "Since docetaxel is a substrate for multidrug resistance transporters such as P-glycoprotein, docetaxel efflux may be enhanced in BRCA2-mutated prostate cancers." (PMID 28676659, 2017). "Men that carrier BRCA2 germline mutations are at risk of developing prostate cancer." (PMID 28067867, 2017). "The key question that arises from our findings is whether a taxane based chemotherapy in prostate cancer patients with a BRCA2 mutation is the optimal treatment considering our finding that the RR in these patients was only 25%." (PMID 28676659, 2017). "Taken together, these results show that BRCA2 mutations can be detected in a substantial proportion of high-risk prostate cancer patients and that the presence of a BRCA2 mutation is associated with a poor response to docetaxel in the majority, but not all patients." (PMID 28676659, 2017). "In addition, a better understanding of the molecular basis of taxane resistance in BRCA2 mutated prostate cancer is needed for strategies to re-sensitize patients." (PMID 28676659, 2017). "Increased risk of prostate cancer (PCa) is observed in men with BRCA1/BRCA2 mutations." (PMID 28812325, 2017). "Mutations in BRCA1 or BRCA2 define a subset of prostate cancer patients." (PMID 28676659, 2017). "Inherited BRCA2 heterozygosity is associated with elevated prostate cancer risk." (PMID 27555886, 2016). "The occurrence frequency of prostate cancer in males with BRCA2 mutations is approximately 5 times higher than expected in the general population and the risk to develop pancreatic cancer in males and females with a BRCA2 mutation is 82.5 times higher and approximately 14 times higher, respectively." (PMID 25632310, 2015). "The association between prostate cancer and BRCA2 is consistent within research." (PMID 26236408, 2015). "Also, higher risk of prostate cancer was recently detected in males with mutations in the BRCA2 OCCR region." (PMID 22923021, 2012). "The germline BRCA2 mutation is associated with increased prostate cancer (PrCa) risk." (PMID 20736950, 2010).